MSH3 (mutS homolog 3)
Diseases named in the same sentence as MSH3 in open-access papers (continued):
Sharing a sentence is not in itself a finding about the gene and the disease.
osteosarcoma (2 papers, 2022 to 2024). A usually aggressive malignant bone-forming mesenchymal neoplasm, predominantly affecting adolescents and young adults. "CRISPR-Cas9-mediated knockout of MSH6, MSH3, and MLH1 in U2OS osteosarcoma cells resulted in the complete loss of each protein (Figure S2A22)." (PMID 38749429, 2024). "Bioinformatic analysis showed the two germline mutations (MSH3 and ERCC4) induced deficiency in the DNA repair machinery, which resulting in the accumulation of mutations and may generate neoantigens contributing to the development of a secondary osteosarcoma in this case." (PMID 36271359, 2022). "In order to reveal the potential genetic mechanism of secondary osteosarcoma occurrence, we analysis the result of whole-exome sequencing and found 8 germline gene variations, which consist of 7 germline genes (including EPAS1, SETD2, MSH3, BMPR1A, ERCC4, CDH1 and AR)." (PMID 36271359, 2022).
renal cell carcinoma (2 papers, 2023 to 2024). "Overexpression of MSH3, particularly under conditions of glucose starvation and concurrent SLC7A11 overexpression, has been demonstrated to promote disulfidptosis in renal cell carcinoma (RCC) cells." (PMID 38685115, 2024).
sarcoma (2 papers, 2020 to 2022). A usually aggressive malignant neoplasm of the soft tissue or bone. "As recurrent mutations in MSH3 and MLL3 have not been described for sarcomas, their exact role in the pathobiology of DSRCT remains unclear." (PMID 32393201, 2020).
anemia (1 paper, 2023). A reduction in the number of red blood cells, the amount of hemoglobin, and/or the volume of packed red blood cells. "Germline variants of DNA repair genes including in addition to BAP1 several members of the Fanconia anemia complementation group (FANC) family as well as MSH3 have been reported in PM." (PMID 36683050, 2023).
bowel cancer (1 paper, 2021). "In this case-control study, mutations in 8 genes (APC, ATM, MLH1, FANCD2, MSH3, MSH6, PMS1, and RAD51D) were found to be associated with bowel cancer and were present in 3.5% of patients with bowel cancer." (PMID 35154239, 2021).
breast tumors (1 paper, 2016).
cognitive decline (1 paper, 2022). "We have replicated previous findings that cognitive decline is slower in carriers of the 3a allele in the gene MSH3, and further showed that slower cognitive decline is supported by the slowing of GM volume atrophy in the cortex, in agreement with the role of MSH3 in somatic instability." (PMID 36519153, 2022).
deficiencies (1 paper, 2023). "It is worth highlighting the interesting tradeoff: Loss of Msh3 may protect against expansions but, on the other hand, can result in MMR deficiencies, as seen in human cancers." (PMID 37127331, 2023).
diffuse large B-cell lymphoma (1 paper, 2013). "Following multiple-testing correction, one SNP in MSH3, a mismatch repair gene, showed an association with diffuse large B-cell lymphoma (OR: 1.91; 95% CI: 1.41–2.59; uncorrected p = 0.00003; corrected p = 0.010)." (PMID 24098683, 2013).
dysplasia (1 paper, 2019). A usually neoplastic transformation of the cell, associated with altered architectural tissue patterns. "UC, UC with dysplasia, and UC-derived CRCs demonstrated dinucleotide or longer microsatellite frameshifts, with UC showing coincident reduction of nuclear MSH3 expression." (PMID 31789935, 2019).
familial adenomatous polyposis type 4 (1 paper, 2023). "The MSH3 gene is associated with familial adenomatous polyposis type 4, of autosomal recessive inheritance (OMIM:617100)." (PMID 37895483, 2023).
gastric cancer (1 paper, 2020). A primary or metastatic malignant neoplasm involving the stomach. "In gastric cancer, MSH3 was the most common mutation, occurring in 74% (37/50) patients." (PMID 32621174, 2020).
gastric leiomyoma (1 paper, 2014). A rare benign smooth muscle neoplasm arising from the wall of the stomach. "The genes found methylated in the gastric leiomyoma play different functions in the cell: MLH1, MSH3, MGMT, and MSH6 participate in DNA repair functions whereas APC gene participates in cell proliferation." (PMID 25544907, 2014).
gliosarcoma (1 paper, 2021). A rare histological variant of glioblastoma (WHO grade IV) characterized by a biphasic tissue pattern with alternating areas displaying glial and mesenchymal differentiation (WHO). "Strikingly, we found a hypermutated phenotype in our patient’s specimen, including mutations in MMR genes, MSH3 and MSH6, which previously have not been associated with gliosarcoma pathology." (PMID 33580181, 2021).
idiopathic male infertility (1 paper, 2021). "The rs26279 variant in MSH3 is associated with idiopathic male infertility, which makes it a possible risk factor for idiopathic male infertility." (PMID 34209597, 2021).
insulin-dependent diabetes (1 paper, 2021). "Pembrolizumab and nivolumab (targeting the protein encoded by MSH3) have been reported to induce the development of insulin-dependent diabetes in cancer patients." (PMID 34230558, 2021).
kidney cancer (1 paper, 2023). Primary or metastatic malignant neoplasm involving the kidney. "Our study showed that MSH3 expression was negatively correlated with the amount of Tregs cells, which play a role in promoting tumor development and immune evasion in kidney cancer." (PMID 37426643, 2023).
leukopenia (1 paper, 2025). "The absence of the rs1127354 (ITPA), rs408626, and rs442767 (MSH3) variants is associated with a higher risk of leukopenia." (PMID 41301675, 2025).
leukoplakia (1 paper, 2013). A white patch or plaque on a mucous membrane that cannot be characterized clinically or pathologically as any other disease. "The present study suggests that MSH3, XRCC5, MRE11A and PRKDC to be the four most important genes that would modify the risk of predisposition to oral cancer and leukoplakia in these eastern Indian populations." (PMID 23437280, 2013). "We performed a case-control association study to identify risk SNPs at major DSB repair (RAD50, MRE11A, NBS1, PRKDC, XRCC5, XRCC6 and LIG4), MMR (MSH6 and MSH3) and key DNA damage response (ATM and ATR) genes in oral cancer and leukoplakia patients from the state of West Bengal of eastern India." (PMID 23437280, 2013).
lymph node metastasis (1 paper, 2023). "Significant relationships determined between KRAS exon 2 and mucinous morphology, PIK3CA and absence of perineural invasion, BRAF and tumor differentiation and localization, MSH3 and tumor diameter, and BRCA2 and absence of lymph node metastasis were findings that have contributed to the literature." (PMID 37737217, 2023).
lymphoma (1 paper, 2022). A malignant (clonal) proliferation of B- lymphocytes or T- lymphocytes which involves the lymph nodes, bone marrow and/or extranodal sites. "The study of the association of MSH3 gene mutations with the number of aberrant STR loci can provide us with a simple method for assessing MMR deficiency in lymphomas by the instability of the tumor STR profile." (PMID 35621668, 2022).
metastasis (1 paper, 2023). The spread or migration of cancer cells from one part of the body (where they first appeared) to another. "Statistically significant relationships were present between KRAS exon 2 and mucinous morphology, PIK3CA and absence of perineural invasion, BRAF and tumor differentiation/localization, MutS homolog 3 (MSH3) and tumor diameter, and BRCA2 and absence of lymph node metastasis." (PMID 37737217, 2023).
myelodysplastic syndrome (1 paper, 2013). A clonal hematopoietic disorder characterized by dysplasia and ineffective hematopoiesis in one or more of the hematopoietic cell lines. "Four of these polymorphisms were located in oxidative damage/DNA repair genes (LIG1, RAD52, MSH3 and GPX3), which may play important roles in the pathobiology of myelodysplastic syndromes." (PMID 23339595, 2013).
myelogenous leukemia (1 paper, 2012). "MSH3 mRNA was not detectable in hematologic progenitor cells of patients with lymphocytic and myelogenous leukemia suggesting that inactivation of the MSH3 gene may be involved in the development of hematologic malignancies." (PMID 23209772, 2012).
pancreatic adenocarcinoma (1 paper, 2021). "Similar frequencies of MSH3 mutations and copy number alterations are found for pancreatic adenocarcinomas, but no MSI-H is evident." (PMID 34298744, 2021).
polyp (1 paper, 2019). A usually exophytic mass attached to the underlying tissue by a broad base or a thin stalk. "We have previously observed evidence for MSH3 dysfunction within hamartomatous polyp epithelium, whose polyp is a non-neoplastic lesion that possesses an expanded inflammatory lamina propria." (PMID 31789935, 2019).
serous ovarian cancer (1 paper, 2010).
small cell lung carcinoma (1 paper, 2022). Small cell lung cancer (SCLC) is a highly aggressive malignant neoplasm, accounting for 10-15% of lung cancer cases, characterized byrapid growth, and early metastasis. "However, inactivation of MMR genes like MSH3 and MSH5 by methylation and single nucleotide polymorphisms (SNPs) has been associated with increased sensitivity to cisplatin-based chemotherapy in small cell lung carcinoma (J.-Y." (PMID 36076047, 2022).
spinocerebellar ataxia type 2 (1 paper, 2025). A subtype of type I autosomal dominant cerebellar ataxia (ADCA type I) characterized by truncal ataxia, dysarthria, slowed saccades and less commonly ophthalmoparesis and chorea. "Evox is developing therapies for diseases with well-defined genetic drivers, including Spinocerebellar Ataxia type 2 (SCA2) via ATXN2 targeting, and Huntington’s disease through MSH3 suppression, with potential relevance to other repeat expansion disorders." (PMID 41155971, 2025).
squamous cell carcinoma (1 paper, 2020). A carcinoma arising from squamous epithelial cells. "For MSH3 rs26784, patients with squamous cell carcinoma carrying CC had longer PFS when compared with CT and TT." (PMID 32742474, 2020). "For MSH3 rs6151670, patients with squamous cell carcinoma carrying GG or GC had shorter PFS when compared with CC." (PMID 32742474, 2020). "For MSH3 rs1650665, patients with squamous cell carcinoma carrying GA or GG had longer PFS." (PMID 32742474, 2020).
tumour syndromes (1 paper, 2021). "Hence, mutational profiles generated by routine tumour sequencing might be particularly helpful in terms of identifying very rare hereditary tumour syndromes, such as MSH3-related adenomatous polyposis." (PMID 34843512, 2021).
Vertigo (1 paper, 2022). An abnormal sensation of spinning while the body is actually stationary. "Fetal brain-based TWAS identified 20 cis-regulated expression genes associated with vertigo, such as MXRA7 (PTWAS = 0.006), MSH3 (PTWAS = 0.018), and DHFR (PTWAS = 0.038)." (PMID 36519156, 2022).
cancer (91 papers, 2010 to 2026). A tumor composed of atypical neoplastic, often pleomorphic cells that invade other tissues. "Mismatch repair genes MLH1, PMS2 and MSH3 displayed an increased number of pathogenic alleles and were linked to cancer phenotypes, suggesting potential limitations as drug targets." (PMID 39801710, 2025). "Clinical genetic repositories analysis showed DNA repair genes, such as MLH1, PMS2 and MSH3, are associated with cancer phenotypes, suggesting potential limitations as drug targets." (PMID 39801710, 2025). "Elevated microsatellite alterations at selected tetranucleotide repeats (EMAST) are a distinct form of genomic instability associated with deficient MSH3 expression, which has been proposed as a potential biomarker in several cancers." (PMID 39451731, 2024). "These prior mechanistic studies support our association and suggest that loss of MSH3 in cancer cells results in an increased rate of accumulation of indels of 2 bp and longer." (PMID 35764656, 2022). "Aberrant MSH3 protein expression and loss of heterozygosity of MSH3 markers have been reported in MSI-L cancers." (PMID 34298744, 2021). "Down-regulation of MSH3 was also more frequent in MSI-H or CIMP-H cancers but the strongest association was observed with MCC methylation (p = 0.0001)." (PMID 34298744, 2021). "The aberrant methylation of other genes, such as FHIT, HOXA9, NNK, and MSH3 have also been found to be associated with cancer progression." (PMID 34456184, 2021). "Msh3 was the only gene with a high-impact mutation that was involved in a significantly altered pathway, a cancer pathway (p-value = 0.0236)." (PMID 32168507, 2020). "Thirteen of them were variants predicted as pathogenic by in silico tools, identified in well-known CRC predisposing genes such as APC and MUTYH, as well as variants in newly emerging cancer predisposing genes such as MSH3 and FAN1." (PMID 32635641, 2020). "The Cancer Genome Atlas (TCGA) project reported MSH3 variants in 40% of hypermutated tumors of which 3/4 were MSI-H." (PMID 28002797, 2017). "Given the lack of evidence for mutation and epigenic inactivation, the defect for MSH3 to cause EMAST had to be an acquired trait for the cancer, and commensurate with this idea is the increased prevalence of EMAST along the adenoma-to-carcinoma continuum." (PMID 25836926, 2015). "Mutation of MSH3 itself can occur as a consequence of MSI-H cancers (sporadic or Lynch) due to its exon 7 coding [A8] microsatellite that can be subject to frameshift." (PMID 25836926, 2015). "We provide evidence that MSH3 can modulate the extent of DNA damage and the cytotoxicity of anti-cancer drugs, and demonstrate that MSH3 deficiency can suppress HR that repairs DSBs." (PMID 23724141, 2013). "In Black South Africans, we observed a marginal association (P = 0.086) for MSH3 rs1428030 polymophism (GG or AG versus AA) with a 1.36-fold increase in cancer risk after adjusting for other confounders." (PMID 22623965, 2012). "In the Mixed Ancestry group, the MSH3 rs26279 G/G versus A/A or A/G genotype was positively associated with cancer (OR = 2.71; 95% CI: 1.34–5.50)." (PMID 22623965, 2012). "In the Mixed-ancestry group, the MSH3 rs26279G/G versus A/A or A/G genotype was positively associated with cancer (adjusted OR = 2.71; P = 5.71×10−3)." (PMID 22623965, 2012). "Some potentially functional variants of MSH3 may influence the DNA repair capacity and thereby predispose individuals to a variety of cancers." (PMID 38028594, 2023). "Among others, the MMR gene MSH3 associated with this component in the pan-cancer analysis." (PMID 35764656, 2022).
cancer (continued). "It would have been very interesting to include carcinoma tissue in the study to compare the variant burden and spectrum between early and advanced MSH3-deficient tumours and other MSI- and MSS CRCs, and to identify potential driver genes, relevant for advanced steps of tumourigenesis." (PMID 34843512, 2021). "As a consequence, carcinomas with loss of MSH3 function may have a defect in HR and might respond better to targeted therapies with PARP and/or DNA-PKc inhibitors." (PMID 34298744, 2021). "The hypersensitivity of the MSH3-deficient cancer to DNA-PK inhibition might be exploited in cancer therapy." (PMID 32015826, 2020). "Recent studies reported that EMAST might be caused by loss of MSH3 in cancer cells owing to the effects of tumor micro-environmental factors, such as hypoxia and inflammation." (PMID 30532127, 2018). "With regard to potential mechanisms of CAG expansion it is of interest that MSH3 and MLH3 appear to play relatively minor roles in classical MMR inasmuch as Msh3 and Mlh3 deficiencies result in weak mutator phenotypes and relatively low cancer predisposition phenotypes." (PMID 24204323, 2013). "However, somatic mutations disrupting MSH3 are often found in cancers showing MSI." (PMID 37127331, 2023). "Indeed, we found that this pattern was most profound among the MSH3-mutated cancers." (PMID 36883553, 2023). "Among other cancer susceptibility genes, associations were seen for ATM (p = 0.0013), BRCA1 (p = 0.0015), BARD1 (p = 0.00021), CHEK2 (p = 0.039), RAD51D (p = 0.0065), MSH3 (p = 0.0025)." (PMID 39749474, 2025). "The reduction of ecDNAs, HSRs and DHFR expression upon MSH3 depletion underscores the significance of MSH3 in regulating cDNAs via DNA double-strand break repair and its bearing on drug resistance in cancer." (PMID 40270992, 2025). "Detecting heterozygous PVs in the MUTYH, NTHL1, MSH3, and MBD4 genes poses a clinical challenge for counseling monoallelic carriers about their cancer risk and for establishing rational surveillance protocols." (PMID 40237887, 2025). "DHFR amplification is a well-known MTX-resistance mechanism, and the co-amplification of DHFR and MSH3 is usually observed in MTX-resistant cancer cells." (PMID 38594370, 2024). "Curiously, the MMR genes MutS homolog 6 (MSH6) and MutS homolog 3 (MSH3) also contain coding homopolymers, and these are frequent mutational targets in MMR-deficient cancers." (PMID 38956208, 2024). "Several studies have demonstrated that polymorphism in MSH3 and MSH6 genes are related to the development of various cancers, including breast, head and neck cancer and hepatocellular carcinoma." (PMID 39003369, 2024). "According to the TCGA database immunotherapy pan-cancer data file, the immunotherapy related to MSH3 is shown using a violin diagram." (PMID 37426643, 2023). "Researchers have also found that the content of eccDNA decreased significantly after knocking down MSH3 mRNA, which is involved in the DNA mismatch repair pathway in human cancer cell lines." (PMID 38159253, 2023). "Biallelic mutations in the MSH3 gene have been found in a small number of individuals with recessive adenomatous polyposis (>20 polyps) and a history of CRC and other cancers (brain, stomach, thyroid and small bowel)." (PMID 36768460, 2023). "For instance, shared clonal mutations in driver genes such as ATM, ATRX, BRCA1/2, DAXX, MSH3, and MSH6 are associated with aberrations in major cellular signaling pathways like Pathways in cancer, DNA damage response, and regulation of cell cycle." (PMID 36140756, 2022). "MSH3 copy number alterations show very little overlap with MSI-H that is mostly confined to MSH3 diploid cancers, but tetranucleotide repeat alterations have not yet been captured in the publicly available data." (PMID 34298744, 2021).